ERO1A (endoplasmic reticulum oxidoreductase 1 alpha)
Description:
Oxidoreductase involved in disulfide bond formation in the endoplasmic reticulum. Efficiently reoxidizes P4HB/PDI, the enzyme catalyzing protein disulfide formation, in order to allow P4HB to sustain additional rounds of disulfide formation. Following P4HB reoxidation, passes its electrons to molecular oxygen via FAD, leading to the production of reactive oxygen species (ROS) in the cell. Required for the proper folding of immunoglobulins. Plays an important role in ER stress-induced, CHOP-dependent apoptosis by activating the inositol 1,4,5-trisphosphate receptor IP3R1. Involved in the release of the unfolded cholera toxin from reduced P4HB/PDI in case of infection by V.cholerae, thereby playing a role in retrotranslocation of the toxin.
Synonyms: ERO1-L; ERO1-L-alpha; ERO1L; ERO1-alpha; Ero1alpha; ERO1LA
Tractability: Small molecule: a structure with a bound ligand is known; a high-quality ligand is known; it has a high-quality binding pocket. Antibody: UniProt places it where antibodies can reach, with high confidence; UniProt predicts a signal peptide or a membrane-spanning region; its Gene Ontology location is reachable by antibodies, with medium confidence. PROTAC: ubiquitination databases record sites on it; a small molecule that binds it is known.
Target class: Enzyme; Oxidoreductase
Gene: Protein-coding gene on chromosome 14 (52,639,915 to 52,696,025, reverse strand). Ensembl gene ENSG00000197930.
Subcellular location: Endoplasmic reticulum membrane; Golgi apparatus lumen; Secreted; Cell projection, dendrite
Pathways (Reactome):
Cellular responses to stimuli: Detoxification of Reactive Oxygen Species
Gene Ontology:
Molecular function: flavin-dependent sulfhydryl oxidase activity; protein binding; thiol oxidase activity; FAD binding; oxidoreductase activity; protein-disulfide reductase activity
Biological process: cell redox homeostasis; protein folding; intrinsic apoptotic signaling pathway in response to endoplasmic reticulum stress; release of sequestered calcium ion into cytosol; response to endoplasmic reticulum stress; response to temperature stimulus; cellular response to hypoxia; protein folding in endoplasmic reticulum
Cellular component: endoplasmic reticulum; extracellular region; Golgi lumen; membrane; endoplasmic reticulum lumen; endoplasmic reticulum membrane; intracellular membrane-bounded organelle; dendrite
Genetic constraint (gnomAD): Loss-of-function variants: 16 observed, 19.98 expected, observed/expected ratio (o/e) 0.8, 90% interval 0.54 to 1.22. The upper end of that interval is the gene's LOEUF score, 1.22, which puts it in group 5 of 6, group 1 being the genes least tolerant of losing a copy. Missense variants: 172 observed, 192.06 expected, observed/expected ratio (o/e) 0.9, 90% interval 0.79 to 1.02. Synonymous variants: 73 observed, 67.6 expected, observed/expected ratio (o/e) 1.08, 90% interval 0.89 to 1.31.
Homologues: Orthologues: chimpanzee ERO1A (99% identical), dog ERO1A (96% identical), macaque ERO1A (95% identical), rabbit ERO1A (92% identical), mouse Ero1a (92% identical), pig ERO1A (92% identical), rat Ero1a (91% identical), guinea pig ERO1A (86% identical), tropical clawed frog ero1a (70% identical), zebrafish ero1a (63% identical), Drosophila melanogaster Ero1L (47% identical), Caenorhabditis elegans ero-1 (40% identical). Paralogues in human: ERO1B (61% identical).
Diseases named in the same sentence as ERO1A in open-access papers:
ERO1A is named in the same sentence as 70 diseases in open-access papers, as found by Europe PMC text mining. Sharing a sentence is not in itself a finding about the gene and the disease. The quoted sentences say what the papers report.
breast carcinoma (25 papers, 2006 to 2025). "Their analysis demonstrated that elevated ERO1α expression was significantly associated with reduced overall survival in breast cancer patients." (PMID 41226317, 2025). "We observed a significant association between high ERO1A expression and shorter overall survival in patients with several solid tumors, including lung cancer, breast cancer, liver cancer, and colorectal cancer." (PMID 37769655, 2023). "Latest studies have shown that overexpression of Endoplasmic Reticulum Oxidoreductin 1-α (ERO1A) is associated with poor prognosis of breast cancer and gastric cancer." (PMID 28881752, 2017). "Interestingly, ERO1α plays a significant role in breast cancer progression, with higher expression levels linked to tumor aggressiveness, metastasis, and poor patient outcomes." (PMID 41226317, 2025). "Notably, MDA-MB-231 cells demonstrated higher ERO1α expression than MCF-7 cells, suggesting a potential association between ERO1α levels and the aggressiveness of breast cancer subtypes." (PMID 41226317, 2025). "EN460, I2 and I3 triggered breast cancer cytotoxicity while specifically inhibiting ERO1A in a dose-dependent manner." (PMID 39962052, 2025). "Although luminal breast cancer cell lines generally display low basal levels of ERO1α, their ability to form mammospheres enriches for a stem-like population in which ERO1α is among the most strongly upregulated genes, as demonstrated in MCF-7 and T47D models." (PMID 41226317, 2025). "As a continuation of the study by Varone, ERO1α expression was found to be significantly higher in TNBC compared to Luminal A breast cancer." (PMID 41226317, 2025). "This general oncogenic role of ERO1α aligns closely with our review’s findings in breast cancer, where consistent evidence shows markedly higher ERO1α expression in breast cancer cells compared to normal mammary tissue." (PMID 41226317, 2025). "This led to identifying the pharmacophoric groups of EN460 that are instrumental in promoting ERO1A inhibition and improving its potency by testing the compounds in different settings, in vitro, in vivo, and in breast cancer models." (PMID 39962052, 2025). "In breast cancer, ERO1α enhances the expression of PD-L1 by facilitating oxidative protein folding and augmentation of HIF1α; conversely, depleting ERO1-α inhibited apoptosis of PD-1+ T cells." (PMID 41333024, 2025). "In summary, this systematic review highlights ERO1α as a critical facilitator of multiple oncogenic processes in breast cancer, particularly within basal-like and triple-negative subtypes." (PMID 41226317, 2025). "ERO1A expression levels were significantly higher in the more aggressive and poorly responsive to pharmacological treatment breast cancer type TNBC." (PMID 39962052, 2025). "Authors confirmed that ERO1α expression was significantly higher in breast cancer cell lines and tissues than in normal breast tissue." (PMID 41226317, 2025). "Collectively, these findings support the notion that ERO1α acts as a key driver of cancer progression and represents a promising therapeutic target across multiple cancer types, including breast cancer." (PMID 41226317, 2025). "For breast cancer, the findings in this review clearly align with this broader pattern, reinforcing the idea that ERO1α is hypoxia-responsive but also revealing important subtype-specific nuances." (PMID 41226317, 2025). "Extending the clinical validation of ERO1α as a predictive biomarker in breast cancer should be the primary focus of future research." (PMID 41226317, 2025). "This review offers an in-depth analysis of the multifactorial role of ERO1α in breast cancer development and progression." (PMID 41226317, 2025). "Under these conditions, ERO1α is upregulated and promotes breast cancer cell metastasis through oxidative folding-mediated activation of VEGF-A and ATF4/CHOP/VEGF pathway." (PMID 41333024, 2025).
breast carcinoma (continued). "Despite growing recognition of its role in tumor biology, research on ERO1α remains limited, with only a small number of studies—11 in breast cancer to date—directly investigating its functions, mechanisms, and therapeutic potential." (PMID 41226317, 2025). "Their analysis revealed that both breast cancer cell lines exhibited elevated ERO1α protein and mRNA expression compared to normal human dermal fibroblasts (NHDF)." (PMID 41226317, 2025). "This systematic review provides a comprehensive and integrative analysis of current research on ERO1α in breast cancer, emphasizing its roles in hypoxia response, angiogenesis, immune modulation, and ferroptosis resistance." (PMID 41226317, 2025). "We next examined the protein level of protein disulfide isomerase (PDI) and endoplasmic reticulum oxidoreductase 1 (ERO-1α), two enzymes that promote proper protein folding in the ER and are upregulated in several cancers including breast cancer." (PMID 35712465, 2022). "Taken together, these data indicate that NFIB is a breast cancer metastasis transcriptional regulator which, through increased expression of ERO1A and VEGFA, promotes angiogenesis at the metastatic site." (PMID 33751828, 2021). "Recently, a study has shown that ERO1α promotes immune escape through up-regulation of PD-L1 in breast cancer." (PMID 33615311, 2020). "The same group also reported that overexpression of Ero1α in human breast cancer up-regulates programmed cell-death 1 ligand 1 (PD-L1), a well-known regulator of an immune checkpoint." (PMID 29673197, 2018). "We previously showed that ERO1-α is overexpressed in various types of cancer cell lines and cancer tissues including breast cancer tissues compared with levels in normal cells and normal tissues." (PMID 28160557, 2017). "We have shown that the expression of ERO1-α in human breast cancer tissue and in cell lines was augmented compared with that in normal breast tissue." (PMID 28160557, 2017). "We also analyzed ERO1A expression in breast cancer and normal counterpart tissues from The Cancer Genome Atlas (TCGA) databank and found higher ERO1A levels in the more aggressive basal breast cancer subtype, including TNBC." (PMID 39962052, 2025). "Studies show that ERO1α is overexpressed in breast cancer cell lines and tissues." (PMID 41226317, 2025). "Additionally, in breast cancer, ERO1α inhibits the T cell response by recruiting myeloid-derived suppressor cells." (PMID 41333024, 2025). "Multiple studies have found that ERO1α is highly expressed in aggressive forms of breast cancer." (PMID 41226317, 2025). "LAMB3 has been reported to play a protumorigenic role in CRC through the AKT-FOXO3/4 axis.ERO1A has been reported to be an unfavorable factor in multiple cancers, including pancreatic cancer and breast cancer, with a cancer-promoting effect in HCT116 CRC cells by regulating integrin-β1." (PMID 36209225, 2022). "Silencing Ero1α inhibits growth and metastatic potential of breast cancer cells." (PMID 29673197, 2018). "However, the mechanisms by which ERO1-α expression affects the prognosis of breast cancer are still unclear." (PMID 28160557, 2017). "Moreover, we reported that overexpression of ERO1-α within the tumor was a poor prognostic factor in patients with breast cancer." (PMID 28160557, 2017). "Finally, given the evidence of the involvement of ERO1A in the tumor microenvironment, we analyzed whether ERO1A inhibition impinges on the breast cancer tumor microenvironment." (PMID 39962052, 2025). "Furthermore, TNBC patients with higher expression of ERO1 had a higher risk of tumor recurrence and metastatic spread indicating that ERO1A might be a biomarker for poor breast cancer prognosis and a target for cancer therapy." (PMID 39962052, 2025). "Therefore, it should be clarified whether targeting ERO1-α in tumor cells results in augmentation of T-cell-mediated tumor cell killing in vitro as well as in an immunocompetent mouse model of breast cancer." (PMID 28160557, 2017).
breast carcinoma (continued). "In the human breast cancer cell line MDA-MB-231, ERO1α promoted angiogenesis by facilitating the oxidative folding of the VEGF protein and enhancing VEGF mRNA expression." (PMID 41333024, 2025). "To experimentally gain hints on ERO1A levels in TNBC, we exploited a tissue microarray (TMA) containing one hundred human breast cancer samples previously classified as Luminal A and TNBC." (PMID 39962052, 2025). "Endoplasmic reticulum disulphide oxidase 1-α (ERO1-α) is highly overexpressed in triple-negative breast cancer, including the MDA-MB-231 cell line, and constitutes a marker of poor prognosis in breast cancer." (PMID 38891038, 2024). "In line with this, inhibition of mTORC1 led to a significantly downregulated expression of ERO1α in the PDAC cells PANC-1 and the breast cancer cells MDA-MB-231." (PMID 38610018, 2024). "NFIB overexpression discriminated between metastatic versus non‐metastatic TNBC breast cancer patient‐derived xenograft (PDX) models and NFIB, ERO1A and VEGFA were co‐overexpressed in these samples." (PMID 33751828, 2021). "NFIB is thus clinically relevant: it is preferentially expressed in the poor‐prognostic group of basal‐like breast cancers, and high expression of the NFIB/ERO1A/VEGFA pathway correlates with reduced breast cancer patient survival." (PMID 33751828, 2021). "Altogether, these findings show that Ero1l/ERO1A expression is increased in Nfib/NFIB‐overexpressing models and suggest that the NFIB‐ERO1A axis is critical for metastatic colonization in breast cancer." (PMID 33751828, 2021). "We found that various types of tumors expressed high levels of ERO1-α and that the expression of ERO1-α in breast cancer is a poor prognosis factor." (PMID 28160557, 2017). "Research shows that ERO1α is overexpressed in breast cancer cells and tissues, while its presence is minimal or absent in normal breast tissue." (PMID 41226317, 2025). "Following title and abstract evaluation, 15 articles were excluded as irrelevant because they either did not investigate ERO1α or did not address breast cancer." (PMID 41226317, 2025). "Our review findings in breast cancer are consistent with this mechanism, further emphasizing that ERO1α supports VEGF-A activity not at the level of gene transcription, but through essential post-translational quality control." (PMID 41226317, 2025). "Despite the growing interest in ERO1α and its function in cancer development, there is a lack of comprehensive literature on its expression and impact on various breast cancer subtypes and its correlation with clinical outcomes." (PMID 41226317, 2025). "Notably, we found that high expression of NFIB and the combined signature of ERO1A and NFIB in patients with breast cancer of the basal‐like subtype were predictive of decreased distant metastasis‐free survival and/or overall survival." (PMID 33751828, 2021). "Additionally, ERO1α mRNA was also detected in breast cancer tissues but not in healthy mammary glands." (PMID 41226317, 2025). "While there are no medicines that specifically target ERO1α, this systematic review’s findings should direct future drug development efforts by drawing attention to the significance of ERO1α overexpression in breast cancer and its role in important pathways that promote tumor growth." (PMID 41226317, 2025).
lung adenocarcinoma (12 papers, 2017 to 2024). A carcinoma that arises from the lung and is characterized by the presence of malignant glandular epithelial cells. "Using the CPTAC proteomic data set in lung adenocarcinoma we found that high ERO1A protein expression correlated with both extracellular matrix and matrix modifying enzymes." (PMID 39496753, 2024). "For instance, Wang and colleagues recently reported a five-autophagy-related signature (ITGB4, NLRC4, ATG9B, CDKN2A, ERO1A) based on overall survival in patients with lung adenocarcinoma." (PMID 34252349, 2021). "Using GEPIA, we determined that that ERO1α is considered a bad prognostic indicator in multiple cancer indications including Lung Adenocarcinoma, Hepatocellular Carcinoma, Esophageal Carcinoma, and Diffuse B-Cell Lymphoma." (PMID 33615311, 2020). "Furthermore, miR-218-5p affects lung adenocarcinoma progression through targeting endoplasmic reticulum oxidoreductase 1 alpha." (PMID 37373422, 2023). "Furthermore, increased ER stress, as demonstrated by increased Bip, Chop, PDI, Ero1α and IRE1, and EMT, as demonstrated by increased Vimentin and Snail, is a hallmark of primary lung adenocarcinoma samples from patients." (PMID 28186986, 2017).
lung cancer (12 papers, 2020 to 2025). A malignant neoplasm involving the lung. "Elevated expression of Endoplasmic Reticulum Oxidoreductase 1 Alpha (ERO1A) in lung cancer patients was linked to an increased risk of recurrence after neoadjuvant immunotherapy." (PMID 41372991, 2025). "In human lung cancer, high ERO1A expression is associated with a recurrence of the disease following neoadjuvant immunotherapy." (PMID 38474359, 2024). "In human lung cancer, high ERO1A expression is associated with a higher risk of recurrence following neoadjuvant immunotherapy." (PMID 37769655, 2023). "Our previous study showed that intrinsic activation of tumor ERO1A drives immunosuppression by recruiting regulatory T cells, cancer-associated fibroblasts, and myeloid-derived suppressor cells (MDSCs) in lung cancer." (PMID 37769655, 2023). "Furthermore, a high expression level of ERO1A is associated with higher recurrence risk after neoadjuvant immunotherapy in patients with lung cancer." (PMID 37769655, 2023). "Together, studies suggest that TM anti-immunity in a lung cancer mouse model can be enhanced with combination therapy that could disrupt ERO1A." (PMID 38474359, 2024). "Moreover, the bioinformatics analyses support that the HOTAIRM1/miR-182-5p/ERO1A regulatory axis has significant functions in lung cancer cell proliferation and stemness via regulatory and physical interactions of ERO1A with stemness TFs." (PMID 36289596, 2022). "Among the components of the HOTAIRM1/miR-182-5p/ERO1A axis, higher HOTAIRM1 levels exhibit values in predicting worse survival of lung cancer patients." (PMID 36289596, 2022). "Previous studies revealed that endoplasmic reticulum oxidoreductase 1 alpha (ERO1L) played critical roles in the malignant behaviors of several cancer types, but its role in non‐small cell lung cancer (NSCLC) remained unclear." (PMID 32841447, 2020). "In this study, the HOTAIRM1/miR-182-5p/ERO1A axis may contribute to lung cancer progression via two collaborators, HOTAIRM1 miR-182-5p and ERO1A." (PMID 36289596, 2022).